CXCL2 (C-X-C motif chemokine ligand 2)
Diseases named in the same sentence as CXCL2 in open-access papers (continued):
Sharing a sentence is not in itself a finding about the gene and the disease.
tumor (continued). "However, Peng found that CXCL2 was a major chemokine involved in regulating the recruitment of neutrophils into the tumor immune microenvironment and promoting the production of prometastatic factors with positive feedback." (PMID 35912252, 2022). "These receptors guide the migration of myeloid derived cells from the bone marrow to tumor regions where CXCL1 and CXCL2 are highly expressed, inhibit the activity and proliferation of effector T cells, and stimulate the growth of regulatory T cells, thereby promoting tumor immune escape." (PMID 34630121, 2021). "Additionally, anti-PD-L1 plus anti-TGF-β combination treatment led to upregulation of additional chemokines such as Cxcl1 and Cxcl2 in tumor cells above and beyond those induced by either single treatment alone." (PMID 34030676, 2021). "CXCL2, 3, 8, 10, 13, and 16 were remarkably related to tumor immunity." (PMID 34247149, 2021). "CXCL2 in culture supernatant was also consistently regulated by overexpressing or knocking down CXCL2, which suggested CXCL2 in the tumor microenvironment (TME) might be regulated by autocrine mechanism." (PMID 34474677, 2021). "Notably, administering a CXCR2 (the receptor for CXCL1 and CXCL2) blocking antibody resulted in reduced accumulation of PMN–MDSCs in the colon and subsequently prevented tumor development in inducible models of colitis-associated cancer." (PMID 34065010, 2021). "C/H was more effective for tumor reduction than either CXCL2 or HVJ-E alone." (PMID 33575480, 2021). "This was attributed to an increased expression of CXCL1 and CXCL2 in tumor tissues that could recruit PMN–MDSCs." (PMID 34065010, 2021). "In ovarian cancer, Snail1 accelerates cancer progression via up-regulation of CXCL1 and CXCL2 as well as recruitment of myeloid-derived suppressor cells (MDSCs), which plays a vital role in cancer immunosuppression, tumor angiogenesis, drug resistance and promotion of tumor metastasis." (PMID 34917071, 2021). "Importantly, they express proangiogenic molecules like VEGF and CXCL2 and thus contribute to maintaining tumor growth." (PMID 34681839, 2021). "Tumor models that showed predominant anti-tumor neutrophil function are characterized by relatively high tumor cell production of CXCL2 and other chemokines together with G-CSF/GM-CSF, resulting in the preferential accumulation of activated neutrophils on the expense of other immune cells." (PMID 34572138, 2021). "The siDDX60L and siMYEOV significantly inhibited the expression of chemokine CXCL2, which may potentially affect the tumor microenvironment in PDAC tissues." (PMID 34789165, 2021). "Factors that can promote the anti-tumor neutrophil phenotype include chemokines (e.g., CXCL2, CXCL5, CXCL8, CCL2, CCL3, CCL5, CXCL12 (SDF-1), CXCL16 and IL-8) alone or together with G-CSF/GM-CSF, TNFα, IFNβ, IFNγ, IFNγ together with TNFα, Resolvin D1, hepatocyte growth factor (HGF) and IL-17." (PMID 34572138, 2021). "Moreover, CXCL2 is a powerful chemoattractant for neutrophils and a previous publication has shown that neutrophil extracellular traps can promote tumor cell metastasis to the liver." (PMID 34115261, 2021). "Hence, our present study first demonstrated the critical roles of CXCL2 in omental adipocytes for tumour growth, angiogenesis and peritoneal dissemination of GC cells." (PMID 32439934, 2020). "Here, miR‐3473b inhibitor significantly reduced the exosome‐mediated inflammatory genes including Il6, Ccl1, Ccl2, Ccl5 and Cxcl2 expression in fibroblasts, which suggest the potential role of exosomal miR‐3473b in establishing tumour‐promoting inflammation environment." (PMID 32449597, 2020). "Similarly, OmAd-CM treatment significantly increased immunoreactivity to Ki67 in the GC tumour tissues, but CXCL2 silencing of OmAd significantly suppressed the ability of OmAd to increase Ki67 staining." (PMID 32439934, 2020).
tumor (continued). "Moreover, GN25 treatment upregulated CXCL2 expression as a potential mechanism to recover the pro-tumorigenic immune microenvironment by recruiting tumor promoting myeloid cells." (PMID 33381110, 2020). "In addition, the tumor-derived cytokines CXCL1, CCL3, CXCL2, TIMP-1, and TNF-α, which have been implicated in the generation, migration, and activation of MDSCs at the tumor site, were regulated by the modulation of MDSCs." (PMID 33091036, 2020). "Likewise, OmAd-CM treatment significantly facilitated tumour angiogenesis, but CXCL2 silencing of OmAd significantly suppressed the angiogenic ability of OmAd." (PMID 32439934, 2020). "Furthermore, the differentiation of CXCR2−/− bone marrow progenitor cells into mo-MDSCs was markedly reduced compared with the WT mice in the serum of tumor-bearing mice or tumor-bearing mice supplemented with recombinant CXCL1 or CXCL2." (PMID 31395859, 2019). "The results showed that the serum of tumor-bearing mice exhibited a substantially increased proportion of mo-MDSCs than that of control mice and the addition of CXCL1 or CXCL2 induced a greater proportion of mo-MDSCs compared to the serum of only tumor-bearing mice." (PMID 31395859, 2019). "MSC/fibroblast-derived chemokines, including murine CXCL1 and CXCL2 (counterparts of human CXCL8), CCL2 and CCL5 were associated with recruitment of neutrophils, tumor-associated macrophages and myeloid-derived suppressor cells to TNBC tumors, where they promoted disease course." (PMID 31031757, 2019). "CXCL2 is a well-known chemokine involved in the recruitment of neutrophils and the inflammatory response that is produced by monocytes, macrophages, endothelial cells, fibroblasts, neural tissue, and a variety of tumor cells." (PMID 31541125, 2019). "Acid-induced NF-κB activation downstream promotes the secretion of several cytokines, chemokines, and growth factors (IL1a, IL1b, IL6, IL8, IL23a, CCL5, CCL7, CXCL2, GM-CSF, and G-CSF) that can elicit local cancer aggressiveness, tumor immune escape, and tumor-induced nociception and hyperalgesia." (PMID 30825056, 2019). "While the CXCL2 expression is elevated in the stromal compartment, CXCL5 expression is associated with the mutant Kras status in tumor cells and regulated by NF-κB and in line upregulated in the tumor cells." (PMID 31561620, 2019). "The decrease of CXCL2 and N-cadherin by celecoxib in T3-2D cells may have contributed to suppression of tumor engraftment and metastasis by celecoxib treatment in these cells." (PMID 29396430, 2018). "Activation of the COX-2 pathway was observed to increase the expression of CXCL-2 and other genes, which in turn may recruit immune cells to the tumor area to promote tumorigenesis." (PMID 29396430, 2018). "Indeed, estrogen induces neutrophil expression of a plethora of genes encoding protumoral cytokines/chemokines(e.g. CXCL1, CXCL2, S100A8, S100A9), matrix metalloproteinases(MMP3, MMP9) and COX-2 that are all known to promote tumor growth and metastasis." (PMID 28429725, 2017). "Similar to observations in hemorrhagic areas of the tumor, the presence of RBCs increased mRNA expression of Cxcl1 (KC), Cxcl2 (MIP-2), and Csf1 (M-CSF), suggesting that the activation of macrophages by heme/iron may trigger recruitment of myeloid cells." (PMID 29167669, 2017). "As showed in the western blot result, CXCL2 was found much higher in all HCC tissues compared to the corresponding non-tumor normal tissues, indicating that CXCL2 may play a similar pivotal role to that of IL-8 in HCC development." (PMID 27117207, 2016). "However, the combination of HVJ-E+poly I:C appears to be slightly more effective for tumor regression compared with the combination of HVJ-E+CXCL2." (PMID 27259252, 2016). "An anti-CXCL2 antibody inhibited the tumor suppression by HVJ-E+poly I:C." (PMID 27259252, 2016).
tumor (continued). "Similarly, after co-incubation with PLIGHT- or PαCD3&LIGHT-transfected tumor cells, the mRNA levels of chemokines and vascular adhesion molecules in vascular endothelial cells, such as CXCL-2, CXCL-8, CXCL-12, CCL-21, MADCAM-1, and VCAM-1, rose by about 2- to 5-fold." (PMID 41406950, 2025). "Furthermore, we observed that tumor cells overexpressing SNAIL could promote the secretion of CXCL2 by activating the NF-κB pathway." (PMID 38605400, 2024). "In addition, the SCC7 subcutaneous tumor-bearing model in C3H mice also substantiated Fn’s ability to enhance tumor progression by facilitating cell proliferation, activating NF-κB signaling, up-regulating CXCL2 expression, and inducing M2 macrophage infiltration." (PMID 38637499, 2024). "Angiogenesis is one of the key steps in tumor growth, and CXCL2 may be involved in angiogenesis." (PMID 39770551, 2024). "Expression of the chemokines Cxcl7 and Ccl5 was significantly elevated, and Cxcl2 and Cxcl12 trended upward in H1792ΔSTK11 tumors compared with control tumors when using mouse primers, concordant with the observed changes in tumor immune cellularity and consistent with host responses." (PMID 37092555, 2023). "Interestingly, the enhanced release of CXCL2 from ITGB4 KD PC-3 cells could be reversed by treating the tumor cells with the STAT inhibitor fludarabine." (PMID 36932441, 2023). "Additionally, the cytokine marker gene CXCL2 was also significantly upregulated in cluster 3 ECs, indicating that the cells may also be involved in tumor-related inflammation." (PMID 37533434, 2023). "Cxcl2, Ccl2, Ccl3, and Ccl8 can act as chemoattractants for myeloid cell recruitment in tumors, while Csf1, Csf2, and Csf3 are central to controlling the recruitment, proliferation, and differentiation of immunosuppressive myeloid cells, including macrophages and neutrophils in the tumor." (PMID 37138326, 2023). "In addition, the decrease in CXCL1 and CXCL2 in tumor tissue induced by WGP may be related to MDSCs." (PMID 36713833, 2023). "Therefore, our results indicated a significant role for CXCL2 in tumor immune escape." (PMID 36281171, 2022). "Finally, clinical strategies aimed at targeting MDSC recruitment into the tumor microenvironment, such as via CXCL2 inhibition, may be critical to overcoming immunosuppression." (PMID 36698398, 2022). "On the other hand, CXCL1 and CXCL2, that are produced upon appropriate stimulation by a variety of cell types including monocytes/macrophages, neutrophils, epithelial cells and also tumor cells, have functions beyond attracting neutrophil granulocytes to the site of infection or damage." (PMID 32276475, 2020). "The combination treatment caused increased secretion of CCL2, CCL21, CXCL1, CXCL2, CXCL5, CXCL9 and CXCL16, whereas the levels of CCL11, CCL17, CCL19, CCL22, CCL25, CCL27 and CX3CL1, which are associated with protumourigenic effects, were decreased in the tumours." (PMID 33014356, 2020). "Inflammatory CC (CCL2, CCL3, CCL5) and CXC (CXCL1, CXCL2, CXCL5, CXCL6, and CXCL8) chemokines recruit at the tumor site CCR2+ monocytes and CXCR2+ neutrophils that differentiate into tumor associated macrophages (TAMs) and tumor associated neutrophils (TANs), exerting pro- or anti-tumoral role." (PMID 30894861, 2019). "Using this approach, we found that CCL2 and CXCL2, which are chemotactic for inflammatory monocytes and granulocytes, respectively, were secreted at higher levels by all metastasis-derived cell populations compared to primary tumor explants and the parental cell line." (PMID 25882816, 2015).
tumor (continued). "In comparison, mouse fibroblasts from KPT tumors were enriched with cells highly expressing tumor-suppressing inflammatory CAF (iCAF) markers, including Has1, Ccl2, Il6, and Cxcl2 (clusters 1–3)." (PMID 41480763, 2026). "We used anti‐CXCL2 and anti‐CXCL6 to neutralize the corresponding chemokines in the culture medium of tumor cells." (PMID 39733452, 2025). "GSDMC2/3/4‐mediated pyroptosis in tumor cells leads to the release of high mobility group protein B1 (HMGB1), which enhances the expression of chemokine attractant C‐X‐C motif chemokine 2 (CXCL2) in surrounding tumor cells." (PMID 40213993, 2025). "Such innate immune cells are recruited to chronically inflamed tissues and tumours by diverse chemoattractants, including CXCL1, CXCL2, CCL2, CCL3, CCL4 and more chemokines and cytokines." (PMID 40434054, 2025). "Our findings are consistent with these results, as G31P inhibited CXCL1, CXCL2 and TNF-α in tumor and bleomycin-induced lung tissues, alongside decreased MPO activity and F4/80+ macrophage infiltration." (PMID 41425704, 2025). "Myeloid-derived suppressor cells (MDSCs), another subset of immunosuppressive regulators in TME, are recruited to tumor beds through CXCL1- and CXCL2-dependent chemotaxis." (PMID 41303712, 2025). "Activation of GSDMC2/3/4 induces tumor cell pyroptosis and facilitates the release of HMGB1, which enhances the expression of CXCL2 in tumor cells." (PMID 40213993, 2025). "One approach is to stop the chemokines such as CXCL1, CXCL2, and CXCL8 (IL-8) that draw neutrophils to the tumor site to prevent their recruitment and usual overexpression in the tumor microenvironment." (PMID 41267750, 2025). "As CSCs acquire enhanced immune evasion capabilities through epigenetic editing, they secrete substantial amounts of factors such as GM-CSF, CXCL1, CXCL2, and CXCL8, which recruit MDSCs to the tumor core." (PMID 41368628, 2025). "CXCL1, CXCL2 and CXCL8 proteins were almost completely removed from the tumours after AEFs treatment." (PMID 39161078, 2025). "In parallel, ERO1α has also been shown to modulate the tumor immune microenvironment—specifically, it enhances the oxidative folding and secretion of immunosuppressive cytokines such as G-CSF, CXCL1, and CXCL2, which are instrumental in recruiting PMN-MDSCs." (PMID 41226317, 2025). "Under stress, macrophages in the PMN release a variety of proinflammatory factors, such as TNF-α, MIP-2/CXCL2, MIP-1β/CCL4, CCL2/MCP-1, sICAM-1/CD54, and G-CSF, all of which promote tumor activity." (PMID 40109727, 2025). "A number of ligands, including CXCL1, CXCL2, CXCL5, and CXCL8, converge on CXCR2, thereby coordinating neutrophil recruitment, angiogenesis, epithelial–mesenchymal transition, and tumor proliferation." (PMID 40943634, 2025). "The activation of GSDMC in tumor cells promoted tumor progression through facilitating the release of HMGB1 and CXCL2‐dependent recruitment of MDSCs to orchestrate the immunosuppressive microenvironment." (PMID 40213993, 2025). "Doublecortin-like kinase 1 (DCLK1), a biomarker of colorectal CSCs, induces the expression of CXCL1 and CXCL2 through the ERK pathway, facilitating the recruitment of MDSCs into an immunosuppressive TME and promoting tumor growth." (PMID 41368628, 2025). "Compared to adjacent normal cells, tumor colonocytes overexpressed chemokines (CXCL1, CXCL2, CXCL3, and CCL20), showing significant effects on inflammatory processes and immune cell recruitment." (PMID 40240912, 2025). "In a murine lymphoma model, ILC2s were able to produce a large amount of the CXCR2 ligands CXCL1 and CXCL2, and interaction with a CXCR2-expressing tumor was shown to induce massive tumor-specific apoptosis in a CXCR2-specific way." (PMID 39858045, 2025). "Neutrophils contribute to the establishment of pre-metastatic niches by secreting chemokines such as ARG1, CXCL1, CXCL2, CXCL10, CCL2, CXCR2, and vascular endothelial growth factor A (VEGFA), which attract tumor cells to metastatic sites." (PMID 40227814, 2025).
tumor (continued). "Numerous studies revealed that chemokines such as CXCL1, CXCL2, IL-8 (CXCL8), CXCL5, CXCL12, CCL2, and MIP-1α (CCL3) promote the infiltration of neutrophil to the tumoural microenvironment." (PMID 40852716, 2025). "Several chemokines and signaling molecules, such as CXCL10, CXCL13, CXCL5, CXCL2, DDR2, and STAT3, have been shown to modulate the tumor microenvironment by facilitating MDSC recruitment and accumulation." (PMID 40051011, 2025). "The bar graphs indicated that the expression profiles of ATF3, CXCL2, RRAD, AREG, and CXCL8 in the C0 subtype were expressed at greater levels than in the remaining tumor cell subtypes." (PMID 40936936, 2025). "Tumor cells and stromal cells secrete a variety of chemokines and cytokines, including cysteine X cysteine ligands such as CXCL1, CXCL2, CXCL5, and CXCL8 (IL-8), that attract neutrophils to the tumor site." (PMID 40227814, 2025). "Circulating neutrophils express the chemokine receptors CXCR1 and CXCR2, and their recruitment to tumour tissues is regulated by CXCL1 and CXCL2, which are the focus of several immune therapy strategies." (PMID 40434054, 2025). "This was verified by the findings that downregulated CXCL2 reduced the infiltration of MDSCs and tumor growth, while early-life microbiota restricted MDSC-driven carcinogenesis by dampening the production of CXCL2." (PMID 40244120, 2025). "Attraction of mobilized neutrophils to the tumor site is realized via chemokines CXCL1, CXCL2, CXCL5, CXCL6, and CXCL8 (IL-8) through CXCR1/2 and CXCL12 (SDF-1) and its receptor CXCR4." (PMID 40050933, 2025). "Genes Ptgs2, Cxcl1, Vegfa, Cxcl2, Col1a1 and Col1a2 were downregulated in cluster 0 of the A101 CAR-T-treated tumor compared to the mock-T-treated group which are involved in angiogenesis and tumor-promoting inflammation as well as EMT and tumor progression." (PMID 40568084, 2025). "In a mouse triple-negative breast cancer (4T1) lung metastasis model, 5-FU elevated ROS in tumor cells, activating NF-κB signaling and upregulating CXCL1 and CXCL2 to recruit neutrophils." (PMID 40805288, 2025). "NLRP4-eco exerted tumor-suppression capacity through chemokine reprogramming including CCL5 and CXCL2." (PMID 40087771, 2025). "Genetic ablation or pharmacological inhibition of DYRK1B changed the secretome of PDAC tumor cells to strongly attract macrophages into tumor sites via the overproduction of CCL5, CCL6, CXCL2, and MCSF." (PMID 39863750, 2025). "The attraction of MCs to a tumor requires the action of different chemokines produced by the tumor cells such as the stem cell factor (SCF), CXCL2, CCL2, CCL5, CCL11, CXCL12, CCL15, IL-3, and IL-33." (PMID 41465542, 2025). "In our investigation, we examined the expression of genes connected to stemness in the different tumor cell subtypes and determined that the expression levels of ATF3, CXCL2, RRAD, AREG, and CXCL8 were significantly higher in the C0 subtype." (PMID 40936936, 2025). "It has been shown that secreted CXCL2 in TME can recruit myeloid derived suppressor cells and M2 macrophages, and this leads to suppression anti-tumor response." (PMID 38885192, 2024). "Ligands secreted by START, such as GAS6 and ICAM, lead to a protumoral phenotype acquisition (M2 phenotype) in the IMs, while CXCL2 and GRN, secreted by IMs, trigger tumor growth in START." (PMID 38546390, 2024).